ALK (ALK receptor tyrosine kinase)
Diseases named in the same sentence as ALK in open-access papers (continued):
Sharing a sentence is not in itself a finding about the gene and the disease.
lung adenocarcinoma (continued). "However, for the 12 trials enrolling patients with non-specified NSCLC histology but with mandatory presence of EGFR mutations (n = 6), ALK rearrangements (n = 5), or KRAS mutations (n = 1), the vast majority of enrolled patients (> 90% for each study) had a diagnosis of lung adenocarcinoma." (PMID 37400832, 2023). "Although a significant number of PD-1 positive CD8+ T cells were found in the ALK-positive tumor bed in early lung adenocarcinoma, these PD-1 expressing CD8+ T cells were functionally impaired and did not express interferon-γ mRNA, which could upregulate PD-L1 expression in tumor cells." (PMID 35958559, 2022). "Using targeted next-generation sequencing (NGS) of 1021 cancer-related genes, we found the emergence of a BRAF V600E mutation in the peripheral blood of a patient with ALK-rearranged lung adenocarcinoma after treatment progression on ALK-TKIs, which may explain the resistance." (PMID 33663128, 2021). "However, the acinar pattern was slightly more common than was the solid pattern in patients with ALK rearrangement (6 acinar vs. 5 solid), which is consistent with previous reports in which lung adenocarcinoma with ALK rearrangement was likely to be related to acinar components." (PMID 31455365, 2019). "Oncogenic fusion of anaplastic lymphoma kinase (ALK) with echinoderm microtubule-associated protein-like 4 resulting from genetic rearrangement is observed in 5% of patients with lung adenocarcinoma (Ad-LC), who tend to be younger and never or light smokers and exhibit aggressive invasion." (PMID 29844868, 2018). "In recent years, there have been dramatic advances in the treatment of lung adenocarcinoma because of the development of therapies targeting driver oncogene alterations, for example, drugs targeting the epidermal growth factor receptor (EGFR) mutation or the anaplastic lymphoma kinase (ALK) fusion." (PMID 28145884, 2017). "This study determined the prevalence of anaplastic lymphoma kinase (ALK) rearrangement, and identified the associations of ALK rearrangement with clinicopathologic characteristics and treatment outcomes in patients with surgically-resected stage I-III lung adenocarcinoma." (PMID 29156778, 2017). "Moreover, frequent decrease of FSTL1-BMP4-p-Smad1/5/8-Smad4 pathway observed in smokers and in ALK-fusion or KRAS mutant adenocarcinoma patients may facilitate the understanding of the molecular pathogenesis of lung adenocarcinoma." (PMID 28852126, 2017). "In addition, our study investigated a lung adenocarcinoma patient with ALK-positive." (PMID 29029508, 2017). "The number of treatment options for lung adenocarcinoma (ADC) has increased in recent decades following the identification of sensitizing epidermal growth factor receptor (EGFR) mutations and anaplastic lymphoma kinase (ALK) rearrangements as molecular targets for effective agents." (PMID 28881674, 2017). "The findings of homogeneous ALK gene translocation in lung adenocarcinoma samples, and concordant ALK status between primary and lymph node metastasis in this study, suggested that ALK gene translocation is a ubiquitous event, must occur very early in lung adenocarcinoma pathogenesis." (PMID 28887531, 2017). "Patients with lung adenocarcinoma diagnosed and undergoing a mutational analysis at the Karolinska University Hospital, Stockholm, Sweden between January 2009 and September 2015 were divided in three subgroups based on their mutational status (EGFR-, ALK-mutated, unexposed group)." (PMID 28560038, 2017). "Advances in the treatment of patients with lung adenocarcinoma were made with the introduction of molecularly targeted approaches, such as the use of tyrosine-kinase inhibitors for patients with tumors containing activating, sensitizing EGFR mutations and Crizotinib for ALK rearrangements." (PMID 27081085, 2016). "However, whether ALK status in lung adenocarcinomas correlates with histologic subtypes remains unclear." (PMID 27386342, 2016).
lung adenocarcinoma (continued). "Here, we evaluated the feasibility of an antibody-independent CTC isolation system using lung adenocarcinomas that have been tested ALK positive as a model to examine the concordance patterns between CTCs and tumor tissue, and to determine whether CTCs were reproducibly detectable in circulation." (PMID 26993609, 2016). "Therefore, we aimed to explore the potential imaging characteristics of the main tumor and intra-thoracic findings, as well as metastases and infiltration patterns, among patients with advanced-stage (stage IIIB–IV) lung adenocarcinoma and driver mutations in EGFR, KRAS, or ALK." (PMID 27518729, 2016). "However, in ovarian cancer, ALK+ lung adenocarcinoma, and prostate cancer, Egr-1 is oncogenic." (PMID 26136341, 2015). "We report a case of a 54-year-old male with a seven-year survival after being diagnosed with Stage IV epidermal growth factor receptor (EGFR) mutation-negative and anaplastic lymphoma kinase (ALK) mutation-negative adenocarcinoma of the lung, demonstrating an exceptional response to treatment." (PMID 26835190, 2015). "Although the underlying mechanism of lung adenocarcinoma is still under investigation, studies showed that recurrent mutations in the epidermal growth factor receptor (EGFR) and the anaplastic lymphoma kinase (ALK) fusions could change the efficacy of treatment for patients with lung adenocarcinoma." (PMID 24646369, 2014). "ALK rearrangements were observed in 6.92% (55 articles: 918/13275), 0.92% (26 articles: 16/1746), 11.54% (13 articles: 9/78) and 5.97% (13 articles: 4/67) patients with lung adenocarcinomas, squamous carcinomas, adenosquamous carcinomas and large cell carcinomas, respectively." (PMID 24959902, 2014). "Interestingly, although somatic mutation is rare in EGFR/KRAS/ALK-negative lung adenocarcinoma of never-smokers, the PCDHB14 (cell adhesion) Y670S mutation and YTHDF1 (RNA binding) I492V mutations were each found in two cases (12.5%)." (PMID 24576404, 2014). "In conclusion, with advantages such as a low cost and 100% sensitivity, IHC with CST’s D5F3 antibody can serve as a robust diagnostic tool with which to routinely screen lung adenocarcinoma patients with ALK+ in pathology labs that do not have access to VENTANA automated IHC platforms." (PMID 24422905, 2014). "Furthermore, a large gene set derived from microarrays well stratified lung adenocarcinomas in one ALK-mutated and two EGFR/KRAS/ALK-mutation negative subgroups." (PMID 27605195, 2013). "This article reports a case of a patient with EGFR-sensitive mutant lung adenocarcinoma who developed secondary transformation to small cell lung cancer (SCLC) and anaplastic lymphoma kinase (ALK) gene fusion following first-line Osimertinib therapy." (PMID 42290055, 2026). "In this study, 41.83% of 208 patients with early-stage lung adenocarcinoma had EGFR gene rearrangements and 7.69% had ALK gene rearrangements." (PMID 41020204, 2025). "The aim of this study is to detect fusion transcripts in the ALK, RET, ROS1, and NTRK1 genes through next‐generation RNA‐seq on samples obtained from paraffin‐embedded tissue, liquid biopsy, and EBC from 30 lung adenocarcinoma patients undergoing treatment." (PMID 39810398, 2025). "The increasing use of targeted therapies for ALK, ROS1, and RET gene rearrangements has underscored the critical importance of routine genetic screening in patients with lung adenocarcinoma." (PMID 39810398, 2025). "Examples include BCR::ABL1 in LAMA84, a blast phase chronic myeloid leukaemia (CML-BP) cell line and EML4::ALK in NCI-H2228 (also known as H2228), a lung adenocarcinoma cell line." (PMID 41421967, 2025). "Three lung adenocarcinoma samples with known EML4-ALK status as determined by qRT-PCR and FISH were analyzed for ALK protein expression using the D5F3/VENTANA and BP6165/LYNX480 PLUS immunohistochemical assays, respectively." (PMID 40017673, 2025).
lung adenocarcinoma (continued). "This study demonstrated the potential role of radiomics and TIME characteristics in identifying ALK rearrangements in lung adenocarcinomas and the prognostic value of radiomics in predicting DFS in patients with ALK rearrangements." (PMID 40376302, 2025). "In conclusion, our results support the potential role of radiomics and TIME in identifying ALK rearrangements in lung adenocarcinomas and the prognostic value of radiomics in predicting the DFS of patients with ALK rearrangements." (PMID 40376302, 2025). "The top five actionable alterations in lung adenocarcinomas were reported in EGFR (43 %), ALK (5 %), BRAF (5 %), KRAS (5 %), and ROS1 (2 %) genes." (PMID 40821453, 2025). "Targeted therapies directed at fusion proteins resulting from ALK, ROS1, RET, and other gene fusions underscore the importance of routinely identifying these alterations in patients with lung adenocarcinoma." (PMID 39810398, 2025). "Herein, we first report a lung adenocarcinoma patient with the coexistence of a novel subfamily 3 of ELMOD (ELMOD3)-ALK, EML4-ALK double fusion that is sensitive to alectinib target therapy." (PMID 40297141, 2025). "During the study, 2343 patients with advanced lung adenocarcinoma were diagnosed, including 1167 EGFR+, 327 ALK+, 98 ROS1+, and 56 RET+ patients." (PMID 40751559, 2025). "Crizotinib, on the other hand, inhibits tumor progression by inhibiting ROS1 or ALK and has been approved for the treatment of advanced lung adenocarcinoma patients with c-ROS1 (ROS1) and anaplastic lymphoma kinase (ALK) gene rearrangements." (PMID 40696350, 2025). "In this study, we developed radiomics, clinicopathological, and combined models for predicting ALK rearrangements in lung adenocarcinomas and the DFS of patients with ALK rearrangements." (PMID 40376302, 2025). "This case deepens our understanding of ALK+ NSCLC with diverse genomic alterations and provides insight into the new treatment of EML4-ALK+ lung adenocarcinoma with multiple gene fusions." (PMID 40052122, 2025). "This is the first case presenting a rare coexistence of a novel ALK double fusion, namely, ELMOD3-ALK and EML4-ALK, in a patient with lung adenocarcinoma who demonstrated favorable sensitivity to alectinib." (PMID 40297141, 2025). "From 2022 onwards, keywords such as “integrated analysis”, “positive NSCLC”, “lung adenocarcinoma”, and “lorlatinib” have emerged as new hotspots, indicating that future research will focus on ALK-positive NSCLC, particularly lung adenocarcinoma." (PMID 40894217, 2025). "Here, we reported a case with concomitant ALK rare double-fusion, namely PLEKHA7-ALK and INPP5D-ALK in a patient diagnosed with lung adenocarcinoma who showed favorable response to alectinib following chemotherapy failure." (PMID 38379102, 2024). "Subsequent investigations demonstrated that inhibiting YAP1 genetically or pharmacologically suppressed tumor growth in ALK-TKI-resistant lung adenocarcinoma cells, EML4-ALK transgenic mice, and tumor xenograft models." (PMID 38499647, 2024). "Similar lineage transitions are observed in other cancers treated with targeted therapies, for example, EGFR-, ALK- and KRASG12C-mutant lung adenocarcinoma, underscoring the broad relevance of lineage plasticity in tumor progression and therapy resistance." (PMID 39394434, 2024). "We considered colorectal cancer with microsatellite instability (MSI), lung adenocarcinoma that is PD-L1 positive, EGFR wildtype, and ALK wildtype, as well as lung squamous cell carcinoma that is PD-L1 positive." (PMID 38709075, 2024). "A 48-year-old male was diagnosed with lung adenocarcinoma, cT4N3M1a, stage IVA with ALK rearrangement, high PD-L1 expression with a tumor proportion score (TPS) of 100%, and MSI-high." (PMID 37114121, 2023). "Anaplastic lymphoma kinase (ALK)-positive NSCLC accounts for only 2%-5% of all NSCLC cases, and is almost exclusively detected in patients with lung adenocarcinoma." (PMID 36792084, 2023).
lung adenocarcinoma (continued). "Therefore, LUSC and lung adenocarcinoma should be discussed separately in terms of adjuvant clinical implementations, and patients with driver gene mutations, including EGFR sensitive mutations or ALK fusions, were excluded from the present study in order to eliminate the systematic bias." (PMID 37188197, 2023). "Since the fusion of echinoderm microtubule-associated protein like-4 (EML4)−anaplastic lymphoma kinase (ALK) was discovered in non-small cell lung cancer (NSCLC), ALK rearrangements have been reported in 3–8% of lung adenocarcinomas." (PMID 36081848, 2022). "The presence of an ALK rearrangement protein has been discovered in a small percentage of NSCLC patients, mostly in those with lung adenocarcinoma." (PMID 36338735, 2022). "Also, no other common lung adenocarcinoma driver mutations such as EGFR or ALK were detected." (PMID 35864317, 2022). "A high prevalence of EGFR and ALK mutations was found in the lung adenocarcinoma of non-smokers with better survivals, which may benefit from the invention of suitable target therapies, and suggested different oncogenic mechanisms of the cancer itself that call for further investigations." (PMID 35847783, 2022). "Such a discrepancy may indicate that the proportion of ALK amplification, as an oncogene driver, is higher than that of an EGFR mutation, or that the application of alectinib is more effective than EGFR-TKIs in the treatment of co-mutated lung adenocarcinoma patients." (PMID 36107507, 2022). "The advent of immune checkpoint blockade (ICB) has led to significantly improved disease outcome in lung adenocarcinoma (ADC), but response of ALK/EGFR-positive tumors to immune therapy is limited." (PMID 34125345, 2022). "All six patients were diagnosed with lung adenocarcinoma and were wild‐type for EGFR, KRAS and ALK‐translocations." (PMID 36251951, 2022). "Second and third-generation ALK-TKI inhibitors have showed better activity and have replaced crizotinib in most of cases of advanced ALK-rearranged lung adenocarcinoma." (PMID 35328235, 2022). "The present study was undertaken to detect ALK gene rearrangements by using immunocytochemistry (ICC) and the FISH technique on cell-blocks, in cases diagnosed as lung adenocarcinoma on cytology samples." (PMID 34514573, 2022). "And the fusions involving ALK and ROS1 preserved the tyrosine kinase domains of these genes as seen in lung adenocarcinoma." (PMID 33441414, 2021). "Patients with newly diagnosed lung adenocarcinoma commonly undergo sequential molecular testing (for EGFR, ALK, ROS1)." (PMID 34918209, 2021). "Mutations in epidermal growth factor receptor (EGFR) and rearrangements in anaplastic lymphoma kinase (ALK) and c‐ros oncogene 1 (ROS1) have emerged as effective therapeutic targets for advanced lung adenocarcinoma." (PMID 33963680, 2021). "EML4/ALK fusion-positive lung adenocarcinoma was predicted to be borderline more sensitive to Alectinib (p = 0.0632) and EML4/ALK or ROS1 fusion-positive lung adenocarcinoma was predicted to be more sensitive to Crizotinib (p = 0.044)." (PMID 34548481, 2021). "Case Report: A 72-year-old patient was diagnosed with a lung adenocarcinoma in February 2018 (EGFR-, ALK-, and PDL1 90%)." (PMID 34046006, 2021). "The application of tyrosine kinase inhibitors against specific gene targets (EGFR, ALK and ROS1) has revolutionized the treatment for lung adenocarcinoma." (PMID 33738250, 2021). "Considering that, according to literature data, there is no more than 20% molecular alterations and rearrangements of the routine biomarkers, such as EGFR and anaplastic lymphoma kinase (ALK), in lung adenocarcinoma." (PMID 33981532, 2021). "Here, we report a case of a 64-year-old Chinese woman who was diagnosed with lung adenocarcinoma (ADC) who concurrently harbored two types of ALK-rearrangements, including an unreported NLRC4-ALK fusion and EML4-ALK fusion." (PMID 32212216, 2020).
lung adenocarcinoma (continued). "Lung adenocarcinomas with ROS1 rearrangement were mainly solid in density (19 of 23, 83%), similar to EGFR-mutant (73%) or ALK-rearranged (88%) tumors, and tended to have a lobulated border (15 of 23, 65%)." (PMID 33005033, 2020). "The positivity rate of ALK is similar in the Asian population with NSCLC (4.9%) and is higher in those with lung adenocarcinomas (6.03%)." (PMID 32266148, 2020). "The National Comprehensive Cancer Network (NCCN) guidelines now recommend routine testing for NTRK, ALK, ROS1, BRAF, and EGFR for all new cases of advanced lung adenocarcinoma for which we have therapies." (PMID 31134065, 2019). "Although ALK inhibitors are effective in most patients with EML4-ALK positive NSCLC, the eventual development of acquired resistance remains a major concern in the treatment of EML4-ALK translocated lung adenocarcinomas." (PMID 30658414, 2019). "Other studies have also reported that lung adenocarcinoma combined with PE is related to a hypercoagulable state and EML4/ALK rearrangement in these patients." (PMID 31568496, 2019). "This incidence was higher than the prevalence of ALK and concomitant ALK and EGFR alterations in multifocal lung adenocarcinomas." (PMID 31861060, 2019). "In the present study, we describe the molecular epidemiology of EGFR, KRAS, BRAF, ALK and MET genetic alterations and their correlations with the demographic and clinical characteristics of 1440 Sardinian patients with lung adenocarcinoma." (PMID 31711449, 2019). "In the lung adenocarcinoma cell line models established in this study, different FA34 subclones showed variable sensitivity to ALK-TKI, and two subclones of FA34 were able to develop resistance to ALK-TKIs." (PMID 30658414, 2019). "The advent of therapies targeting the fusion proteins arising from ALK, ROS1, and RET gene fusions makes the routine detection of these events important in patients with lung adenocarcinoma." (PMID 30115026, 2018). "As far as we know, this study is the first study to compare the efficacy of pemetrexed-based chemotherapy between HER2-mutant and groups of EGFR-mutant, ALK/ROS1-rearranged and KRAS-mutant lung adenocarcinoma." (PMID 29587667, 2018). "This is analogous to adenocarcinoma of the lung where fusion genes involving MET, ROS1, and ALK are all treated with TKIs that are effective against each of the kinase domains." (PMID 29654269, 2018). "In ALK-positive lung adenocarcinoma cell lines and mouse xenograft models, the RAS–MEK pathway was found to be the critical downstream effector of EML4–ALK." (PMID 29495603, 2018). "In this study, we found that a portion of lung adenocarcinoma patients with concomitant EGFR and ALK alterations." (PMID 28887531, 2017). "A 57-year-old male smoker with lung adenocarcinoma of his right lower lobe was positive for EML4-ALK and positive for ALK." (PMID 29207989, 2017). "NSCLC patients harboring rearrangements within the ALK, ROS1 and RET gene can be targeted in lung adenocarcinoma using specific therapies such as Crizotinib." (PMID 28404952, 2017). "We also found a small portion of lung adenocarcinoma samples have concomitant EGFR and ALK alterations by using direct sequencing." (PMID 28887531, 2017). "Previously, we screened for ALK, ROS1, and RET fusion genes in 795 lung adenocarcinoma specimens and identified the novel KIAA1217-RET fusion gene containing KIAA1217 exon 11 and RET exon 11 from a patient with a 4-cm tumor mass (red arrow)." (PMID 27150058, 2016). "The targeted drugs developed for lung adenocarcinoma such as EGFR tyrosine kinase inhibitor (EGFR-TKI) and ALK inhibitor, are largely ineffective against SqCLC." (PMID 27145277, 2016). "Five common oncogenes, Kras, EGFR, ALK, ERBB2, and BRAF are represented in more than 50 % of lung adenocarcinomas." (PMID 26884725, 2016).